TPX2 (TPX2 microtubule nucleation factor)
Diseases named in the same sentence as TPX2 in open-access papers (continued):
Sharing a sentence is not in itself a finding about the gene and the disease.
tumor (continued). "Six overexpressed and mutated tumor antigens associated with poor prognosis and infiltration of antigen presenting cells were identified in PAAD, including ADAM9, EFNB2, MET, TMOD3, TPX2, and WNT7A." (PMID 33648511, 2021). "Hsa_circ_101996 binds to miR-8075 like a sponge, inhibiting the regulatory effect on TPX2 microtubule nucleation factor (TPX2), resulting in upregulation of TPX2 and tumor progression." (PMID 33803232, 2021). "We also analyzed role of TPX2 in tumor immunity and found that TPX2 is involved in the infiltration of B cells, CD4+ T cells, CD8+ T cells, Macrophage cells and Neutrophils cells in OSCC." (PMID 33892811, 2021). "Targeting protein for Xklp2 (TPX2) is positively correlated with the metastasis and growth of tumor cells as well as the clinical stage in NSCLC." (PMID 33988228, 2021). "On the other hand, we were also surprised by the wide variability in nuclear TPX2 expression across our cohort and how strongly this correlated with markers of tumor aggression and poor outcome." (PMID 33622270, 2021). "We found that TPX2 nuclear expression correlated with an increase in tumor size, with larger tumors demonstrating higher TPX2 nuclear expression." (PMID 33622270, 2021). "For other genes, AURKA, PTTG1, CDC20, SLC7A5, E2F8, TPX2, and TUBA4A, high expression in the high-risk group was linked to tumour growth and metastasis." (PMID 34131308, 2021). "Relative to control cells, the suppression of all three genes (TTK, TPX2, and RAD54B) was associated with significant reduction in tumor size (p ≤ 0.04) in SCID mice." (PMID 34031527, 2021). "Several tumours overexpress TPX2, often within signatures of mitotic genes, frequently including Aurora-A." (PMID 32041138, 2020). "Since TPX2 plays an essential role in mitotic spindle apparatus and subsequently cell division and tumor growth via binding to Aurora-A, many researchers focus on identifying antagonists to blockade this interaction." (PMID 32723329, 2020). "Growing evidence has proved that increased TPX2 contribute to the poor prognosis by triggering spindle dysfunctions, subsequent chromosomal instability or abnormal DNA damage response in tumor development." (PMID 33029085, 2020). "And we found that while knocking down FOXM1, the tumor growth was suppressed, and at the same time, the expression of TPX2 was also decreased in vivo." (PMID 32723329, 2020). "Many of the key regulators in the canonical oncogenic (tan) module were involved in the processes leading to tumor cell proliferation and survival (TPX2, NCAPH, KIF11, NUSAP1, KIF23, MCM10) but most of them have not been associated with pediatric tumors." (PMID 31988326, 2020). "Among these, RACGAP1, RARRES3, TPX2, MMP28, GPR87, and KIF14 were upregulated and positively associated with poor survival, whereas TSPAN7 was downregulated and identified as a tumor suppressor." (PMID 33033514, 2020). "As for the protein expression level's validation, it was assessed to indicate that UBE2C and TPX2 expressions were significantly higher in tumor tissues than in normal tissues in accordance with the Human Protein Atlas database." (PMID 32309427, 2020). "TPX2 overexpression is positively correlated with lymphatic metastasis, tumor grade and stage, negatively with the survival rate 22-24." (PMID 33029085, 2020). "Higher levels of both FOXM1 and TPX2 correlated positively with larger tumors, poorer histological grade and later tumor-node-metastasis (TNM) stage." (PMID 32723329, 2020). "Previous studies have shown that TPX2 is overexpressed in tumour tissues and promotes the tumorigenesis of multiple cancers." (PMID 31285741, 2019).
tumor (continued). "Univariate Cox analysis showed that TNM stage, tumor grade, postoperative adjuvant therapy, TPX2 expression and MMP12 expression were significantly associated with DFS (P < 0.05)." (PMID 30305064, 2018). "Further multivariate Cox regression analysis showed that TNM stage, tumor grade, TPX2 expression and MMP12 expression were independent prognostic factors (P < 0.05)." (PMID 30305064, 2018). "Then multivariate Cox proportional hazards regression analysis revealed that TNM stage, tumor grade, TPX2 expression and MMP12 expression were independent predictors (P < 0.05)." (PMID 30305064, 2018). "Several studies have demonstrated that TPX2 is overexpressed in multiple tumor types and promotes tumor growth and metastasis." (PMID 28069036, 2017). "For the upregulated genes, TPX2 (2.8-fold increase) plays a critical role in the chromosome segregation machinery during mitosis and suppresses tumor cell growth." (PMID 29133945, 2017). "Of these samples, 123 (42.4%) were classified as having high TPX2 expression (≥5% of tumor cells stained)." (PMID 28069036, 2017). "The proliferation of the tumor was significantly lower in mice treated with TPX2 siRNA than in mice treated with PBS or Control siRNA." (PMID 25914189, 2015). "In our study, we directly injected TPX2 siRNA into the tumors and found a significant suppression of tumor growth." (PMID 25914189, 2015). "Here, we report that TPX2 expression, like RAN, correlates positively with tumor grade, and was associated with poor patient survival and with a short recurrence time in HG serous EOC." (PMID 24625450, 2014). "Due to these properties TPX2 has been considered a good histological marker for actively proliferating tissues, and hence for tumours, where it has been established that TPX2 expression is altered." (PMID 25401333, 2014). "Molecular studies have shown that down-regulation of RAN results in mitotic defects, the improper localization of TPX2, apoptosis and tumor growth inhibition." (PMID 24625450, 2014). "To decipher the mechanism underlying RanGAP1-knockdown-induced cell-cycle arrest and tumor cell death in DLBCL lines, we tested the effects of RanGAP1 siRNA on the expression of Aurora kinases and TPX2." (PMID 24223200, 2013). "Similar trends for the cell-cycle-associated genes (ASPM, CENPE, TPX2, TRIP13, KIF11, KIF20A) were observed with their distribution in different-grade tumors, with higher expression levels observed as tumor grade increased." (PMID 23506684, 2013). "The TPX2 signature was tumor cell autonomous and predictive of DMFS only in those patients who were ER+ at diagnosis, and was distinct from a CD53 network that was associated with ER-negative stromal components." (PMID 22693453, 2012). "Notably, G6PD was predominantly expressed in early and mid-stages, while KPNA2, PFKP, and TPX2 were upregulated in advanced tumor states." (PMID 40307857, 2025). "There is emerging evidence suggesting that elevated TPX2 protein levels may contribute to poor patient prognosis by influencing immune cell infiltration within the tumor microenvironment (TME)." (PMID 40362354, 2025). "Overall, our findings indicated that TPX2 lactylation might promote tumour growth through regulating the cell cycle." (PMID 40107714, 2025). "To further investigate whether TPX2 is lactylated in vivo, we employed a spontaneous mouse model of HCC by injecting YAP5SA plasmids into mice and detected TPX2 lactylation in HCC tumour tissues in vivo via the IP assay." (PMID 40107714, 2025). "We next evaluated the effect of TPX2 lactylation on the in vivo HCC tumour growth by employing an HCC xenograft mouse model established via the subcutaneous injection of HepG2 cells with endogenous TPX2 knockdown and Flag-TPX2WT or Flag-TPX2K249R re-expression." (PMID 40107714, 2025).
tumor (continued). "In particularly, expression of TPX2 showed strong positive correlations with tumor proliferation signature, G2M checkpoints, DNA damage repair, and DNA replication (all r > 0.5), indicating that tumor proliferation was promoted with increased TPX2 expression." (PMID 38833082, 2024). "Tumor models were established in nude mice to verify the biological functions of TPX2 in vivo." (PMID 38466034, 2024). "Nevertheless, the role of TPX2 in tumor immune landscape remains inadequately explored." (PMID 38315450, 2024). "It has been suggested that TPX2 enhances tumor cell invasion by up-regulating cadherin levels." (PMID 39935706, 2024). "In order to identify the key regulators in the ICD risk subgroups, first we verified the mRNA expression levels of these eight genes, and we found that only SFTPB and SERPIND1 were highly expressed in normal tissues, whereas FAM83A, FDCSP, KRT6A, RHOV and TPX2 were highly expressed in tumor tissues." (PMID 39247599, 2024). "For example, the highly expressed TPX2 in HCC might promote tumor cell invasion via activating AKT signaling and subsequently increasing MMP2 and MMP9 expression." (PMID 39458959, 2024). "We sought to explore the genetic alteration of TPX2 in TCGA tumor samples with cBioportal." (PMID 38315450, 2024). "Additionally, we assessed the correlation between CDC45, CDC20, and TPX2 with tumor stemness using Pearson correlation analysis." (PMID 39114311, 2024). "Moreover, TPX2 overexpression correlates with tumor proliferation, metastasis and poor outcomes in solid tumors." (PMID 38315450, 2024). "Moving forward, experimental validations of TPX2 in each tumor remain imperative." (PMID 38315450, 2024). "For DFI, high TPX2 expression was related to poor DFI in 9 tumor types." (PMID 38315450, 2024). "Similarly, TPX2 expression tended to increase with tumor grade, with grade 3 tumors showing the highest TPX2 expression." (PMID 38833082, 2024). "Moreover, the effect of TPX2 on PXR pathway-related factors was examined with qPCR in subcutaneous tumor tissues." (PMID 36707511, 2023). "The results indicated that TPX2 may be associated with suppressive TME and thus weaken anti-tumor immunity." (PMID 36927438, 2023). "Thus, we examined TPX2 expression in the tumour tissue of 400 resected PDAC patients and tested its effect on patient outcome according to the type of adjuvant treatment they received." (PMID 37142730, 2023). "TPX2 levels were positively connected with tumor proliferation signature." (PMID 36789877, 2023). "Next, whether the effects of TPX2 cause acceleration of a the metabolism and/or clearance of sorafenib, a standard TKI for advanced HCC treatment in HCC cells or HCC tumor tissues were examined by LC–MS/MS." (PMID 36707511, 2023). "Therefore, TPX2 appears to cause an acceleration of the metabolism and/or clearance of sorafenib in HCC cells or HCC tumor tissues." (PMID 36707511, 2023). "Moreover, in subcutaneous tumor models, overexpression of TPX2 promoted the subcutaneous growth of HepG2 cells and sorafenib inhibited the subcutaneous growth of HepG2 cells in a dose-dependent manner." (PMID 36707511, 2023). "Interestingly, after PD-L1/CTLA-4 treatment, CTSO, MMP1, SPP1, and TPX2 were significantly up-regulated in tumor cells." (PMID 36225568, 2022). "This indicates that expression changes of the TPX2/AURKB subnetwork likely reflect tumor intrinsic features while those of the COL1A2 subnetwork likely captures features of stromal cells in the tumor microenvironment impacted by alterations in tumor cell aurora kinase signaling." (PMID 35332150, 2022). "In this study, bioinformatic analysis was performed to investigate the relationship among TPX2 expression, prognosis, clinical stage, tumor mutational burden (TMB), microsatellite instability (MSI), tumor microenvironment, and immune cell infiltration (ICI) in multiple cancers." (PMID 36304254, 2022).
tumor (continued). "Meanwhile, our data indicate that TPX2 is involved in the recruitment and modulation of tumor-immune infiltrating cells, and that for BLCA, LIHC, LUAD, STAD, and UCEC, it might be employed as a predictive biomarker." (PMID 36304254, 2022). "TPX2 expression was significantly correlated with tumor purity (p = 1.23e-03)." (PMID 36686655, 2022). "Additionally, we performed an analysis based on the TCGA database, which showed that the expression of TPX2 positively correlated with that of MKI67 in tumor-infiltrating CD8+ T cells in HCC." (PMID 35273149, 2022). "Furthermore, circRNA_101996 acted as a sponge for miR‐8075, which relieved the repressive effect of miR‐8075 on Xenopus kinesin-like protein 2 (TPX2) expression, subsequently upregulating TPX2 expression and promoting tumor progression." (PMID 35166172, 2022). "However, it should be noted that the spindle assembly function of TPX2 takes place only during the brief period of mitosis, and that only a small minority of tumor cells will be in mitosis at any given time." (PMID 33622270, 2021). "The knockdown of TPX2 increases chromosome mis-segregation and suppresses tumor cell growth in PCa." (PMID 33708770, 2021). "Therefore, we sought to determine if increased expression of TPX2 correlated with markers of cell proliferation, including tumor size and Ki67 index." (PMID 33622270, 2021). "In addition, TPX2 has differential expression in patients with different tumor stages, genders, races, and molecular subtypes." (PMID 33892811, 2021). "Targeting TPX2 relieves ESCA progression through weakening tumor growth and invasion." (PMID 34987580, 2021). "Moreover, TPX2 is differentially expressed in patients with different tumor stages, genders, races, and molecular subtypes according to UALCAN website." (PMID 33892811, 2021). "Xenopus kinesin-like protein 2 (TPX2) was reported to promote tumor invasion and proliferation." (PMID 33195193, 2020). "Indeed, tumour-associated signatures, including TPX2 up-regulation, display overexpression of other cell cycle or mitotic regulators, and particularly of Aurora-A, suggesting that co-deregulation of other factors may underlie chromosomal instability in TPX2-overexpressing cells." (PMID 32041138, 2020). "HMMR and TPX2 were also negatively correlated to patients’ prognosis while no expression difference was observed in diverse tumor grades and CDC20 was positively associated with tumor grade but not correlated to patients’ outcomes." (PMID 32716025, 2020). "Experiments in human tumour cells showed that TPX2 overexpression also affects spindle assembly." (PMID 32041138, 2020). "The TPX2 gene is part of the signature of chromosomal instability from specific genes whose expression was consistently correlated with clinical outcome in multiple human cancers, and it has been identified as a driving oncogene in different kinds of neoplasm." (PMID 31557970, 2019). "TPX2 has been reported to correlate with tumor migration and invasion." (PMID 31272499, 2019). "The oncoprotein TPX2, a key regulator for certain tumor progression, attracted our attention." (PMID 31272499, 2019). "The expression of CCNB2, KIF4A, and TPX2 were upregulated in the advanced tumor stages." (PMID 30254986, 2018). "Among them, CCNB2, KIF4A, and TPX2 were further upregulated in advanced tumor stage." (PMID 30254986, 2018). "These patients were characterized by higher tumor stage and overexpression of TPX2 and MMP12." (PMID 30305064, 2018). "The TPX2 positivity rate was 66.98 % (71/106) in tumor tissues." (PMID 27777511, 2016). "In the multivariate analysis of the prognostic factors, we confirmed that high TPX2 expression was an independent prognostic factor (95 % CI 2.626–7.198; P = 0.001), and age, tumor size, and N stage were also independent and significant prognostic factors for OS (P = 0.046, 0.005 and 0.000)." (PMID 27777511, 2016).
tumor (continued). "Finally, we will briefly discuss the implications of the use of Aurora A inhibitors in anti-tumor therapies in the light of its functional interaction with TPX2." (PMID 27148480, 2016). "TPX2 was predominantly present in the nucleus and cytoplasm of tumor cells." (PMID 27777511, 2016). "The expression level of TPX2 mRNA was significantly higher in tumor tissues (P = 0.002)." (PMID 27777511, 2016). "In addition, the number of Ki67-positive cell in tumor treated with TPX2 siRNA was lower than that in tumor treated with PBS or Control siRNA." (PMID 25914189, 2015). "One possible explanation for the observed metastatic suppression by Tpx2 knockdown might be a reduced ability of cells to escape the primary tumor." (PMID 25368990, 2014). "Our results demonstrate that TPX2 may act as a potent prognostic marker and contribute to tumor growth and metastasis of HCC." (PMID 25302620, 2014). "Histologic analysis suggests instead that variation of TPX2 levels within disseminated tumor cells may influence the transition between dormant to actively proliferating cells in the secondary site." (PMID 25368990, 2014). "The top differentially expressed transcripts between tumor and non-tumor were TPX2, DCBLD2 and ANLN which were significantly increased in tumors (T∶N ratio>2.0, P<0.01), and CDO1, DPEP1, C7, ALDH1A1 and NR3C2 which were significantly decreased in tumors (T∶N ratio<0.2, P<0.01)." (PMID 22363658, 2012). "Importantly, TPX2 lactylation is required for the cell cycle regulation and tumour growth." (PMID 40107714, 2025). "In addition, amplification emerged as the predominant genetic alteration of TPX2 in tumor cases." (PMID 38315450, 2024). "Furthermore, we also analyzed the relation between TPX2 expression and TIDE score, TMB and MSI, indicating that TPX2-low group has higher TIDE score compared to that of TPX2-high group, and the tumor mutation burden of TPX2-high group has higher than that of TPX2-low group." (PMID 38643462, 2024). "Furthermore, Cox regression demonstrated that TPX2 expression could significantly impact the OS of 16 tumor types." (PMID 38315450, 2024). "In addition, TPX2 was reported to promote tumor angiogenesis in PDAC." (PMID 33033514, 2020). "Furthermore, our analysis indicated TPX2 was mostly concentrated in tumor-related pathways." (PMID 33029085, 2020). "Moreover, TPX2 knockdown obviously slowed down tumor growth in a nude mouse xenograft model." (PMID 25302620, 2014). "However, despite being the central node of the proliferation associated network module, the role of TPX2 in metastatic breast cancer can be independent of a role in tumor cell proliferation rates." (PMID 25368990, 2014). "Furthermore, in tumor bearing mice, TPX2 knockdown slows down tumor growth." (PMID 25302620, 2014). "Therefore, TPX2 expression might provide a more precise evaluation of the proliferative behavior of tumor cells." (PMID 24341487, 2013). "In this study, via lactylome analysis of clinical HCC tumours and a series of knockdown and overexpression lines of HCC cells and YAP5SA-induced HCC mouse models, we found that lactate induced TPX2 K249 lactylation in HCC tumour tissues." (PMID 40107714, 2025). "COM exposure led to the downregulation of well-established RCC tumor suppressor genes, including ARID1A, PTEN, and VHL, while significantly increasing TPX2 expression." (PMID 40362354, 2025). "Cluster 13 was exclusively expressed in T1, and the highly expressed markers TOP2A, CENPF, TPX2 and HMGB2 are related to tumour proliferation and malignancy." (PMID 40099956, 2025). "The significant overlap highlights the dual roles of genes such as TOP2A, CCNB2, BUB1, TPX2, and EZH2 in both tumor initiation and tumor progression, reinforcing their potential as key biomarkers for PCa." (PMID 40626556, 2025). "Our results further indicated that the inhibition of lactate production or TPX2 lactylation led to cell cycle delay in HCC cells and suppressed in vivo tumour growth." (PMID 40107714, 2025).